CRP (C-reactive protein)
Diseases named in the same sentence as CRP in open-access papers (continued):
Sharing a sentence is not in itself a finding about the gene and the disease.
Obesity (continued). "In clinical case of obesity, a gradual rise in serum SPX has been reported after bariatric surgery with improvement in BMI and various indicators for insulin resistance (e.g., HOMA-IR and hs-CRP)." (PMID 34025589, 2021). "Overall, a positive correlation was observed between serum concentration of leptin and CRP independent of the obesity indices." (PMID 33680494, 2021). "Most of ceramides, dhCers, and SMs showed unfavorable correlations with obesity (rs = 0.06 to 0.15), triglycerides/HDL-cholesterol (rs = 0.06 to 0.28), CRP (rs = 0.06 to 0.17), IL-6 (rs = 0.07 to 0.13), adiponectin (rs = −0.06 to −0.14), and RBP4 (rs = 0.06 to 0.24)." (PMID 34208976, 2021). "In conclusion, circulating CRP is moderately elevated in PCOS women independent of obesity, which is indicative of low-grade chronic inflammation." (PMID 33800490, 2021). "Although obesity is considered a low-grade systemic inflammatory state, in the present study, we did not observe differences in us-CRP and in most of the cytokines analysed in blood serum (IL-6, TNF-α, IL-1β, IL-10, MCP-1 and leptin)." (PMID 33489104, 2020). "Leptin may upregulate the production of inflammatory cytokines such as CRP, TNF-α, IL-6, and IL-12 and be involved in low-grade inflammation, which plays a central role in the pathophysiology of obesity, depression, metabolic and cardiovascular disease." (PMID 33036196, 2020). "CRP values on day 1 were not significantly different compared to without obesity (73 vs 84 mg/L; p = 0.099)." (PMID 33326480, 2020). "Many studies have shown that KD approaches had an anti-inflammatory effect by reducing inflammatory markers, including C-reactive protein, TNF-α, MCP-1, interleukin-6 (IL-6), and IL-8, which are generally higher in obesity." (PMID 32848830, 2020). "The interactions between CRP, the APOE genotype, cardiovascular diseases and cognitive functions and dementia are confusing and might depend on gender, age, and disease such as obesity." (PMID 32646381, 2020). "LMS was an independent risk factor for NAFLD regardless of age, sex, obesity, DM, HTN, DL, hs‐CRP level, and IR with the odds of NAFLD among individuals with LMS reaching 1.66." (PMID 32638541, 2020). "Markers of inflammation, including CRP and ferritin on the first and second hospital days, were lower among patients with obesity than those without." (PMID 33326480, 2020). "We detected an interesting nonlinear squared correlation between VO2 peak level CRP concentration in women with obesity after the intervention." (PMID 33255278, 2020). "According to the available data from the literature and meta-analyses, adult patients with PCOS have a higher level of CRP not due to obesity, rather due to the presence of the disease itself." (PMID 32397375, 2020). "We found significantly higher values in BMI, waist-hip ratio (WHR), and waist circumference as well as in CRP, white blood cell, glucose, and insulin levels and HOMA-IR, in both groups of patients with obesity compared with lean patients, whereas HDL levels were decreased." (PMID 32244612, 2020). "Subjects with obesity, regardless of their metabolic profile, had higher levels of C-reactive protein Z-score." (PMID 32443557, 2020). "In stratified analysis by obesity, we identified 11 non-obese patients with high pre-RT CRP also had pain scores ≥ 4 at both pre- and post-RT." (PMID 31138314, 2019). "CRP is a generic inflammatory biomarker and is increased with obesity and steatosis, but not NASH severity." (PMID 31291245, 2019). "The reliability estimates were not substantially influenced by participants’ age, sex, obesity status (normal or overweight) and baseline CRP levels." (PMID 31139232, 2019). "Like CRP, SAA is an acute phase protein that is substantially elevated during acute inflammation and is also modestly elevated during chronic inflammatory conditions such as obesity, diabetes, and MetS." (PMID 31151202, 2019).
Obesity (continued). "Nevertheless, our analysis revealed that hs-CRP was not related to LV diastolic dysfunction in adolescents with obesity." (PMID 31120986, 2019). "Our data did not reveal pronounced differences by strata of age, sex, obesity and CRP levels arguing against possible influence of any of these factors on the observed reliability estimates." (PMID 31139232, 2019). "Among the fifteen factors investigated, seven factors, namely, age, cardiovascular disease, cerebrovascular disease, obesity, APACHE II scores, and severity levels of CRP and CAP, were significantly different in deceased patients than in living patients (p<0.05)." (PMID 31291389, 2019). "Alemi and co-authors showed a positive relation between eHSP70 and HOMA-IR but not BMI in patients with T2DM, regardless hs-CRP levels and obesity." (PMID 30840227, 2019). "The etiology of MS involves genetic, metabolic and environmental factors and it usually manifests with insulin resistance and abnormal values of HDL-c, triglycerides (TG), waist circumference (WC), blood pressure, and C-reactive protein (CRP), in addition to obesity." (PMID 31312214, 2019). "According to one study, because CRP is a nonspecific marker of inflammation, it can suffer the influence of a number of factors, including obesity, hypertension, smoking, increased levels of triglycerides, and others." (PMID 31411315, 2019). "CRP is a non-specific marker of inflammation produced by the hepatocytes in the liver, and its concentration is increased in obesity." (PMID 31052485, 2019). "C-reactive protein, diet quality and physical activity did not mediate the effect of obesity on major depressive disorder, and C-reactive protein mediated about 25% of the effect of major depressive disorder on adiposity." (PMID 31800914, 2019). "In multivariate linear regression analysis for LOS with iron deficiency as a binary variable, iron deficiency remained an independent predictor of LOS in HFpEF (b = 2.74, 95% CI 0.32–5.17), after adjusting for CKD, CAD, hypertension, DM, obesity, atrial fibrillation or flutter, COPD, CRP, and age." (PMID 31581494, 2019). "Of note, in participants with inflammation, median CRP was higher in those without severe obesity than those with severe obesity (20.5 vs 19.1 mg/L; P < .001)." (PMID 31469399, 2019). "The reliability estimates were not substantially influenced by participants’ age, sex, obesity and C-reactive protein (CRP) levels." (PMID 31139232, 2019). "CRP, primarily produced in the liver, is known to be upregulated under conditions of obesity, regardless of age, sex, or ethnicity of subjects studied." (PMID 29849871, 2018). "Some confounding factors such as hyperlipidemia, obesity, white blood cell and hypersensitive C-reactive protein were not able to be analyzed because of the small number of studies included." (PMID 30619067, 2018). "Obesity was a significant moderator of the relationship between depressive symptoms and γ-glutamyltransferase (p = 0.02), but not CRP (p = 0.43) or sleep quality (p = 0.93)." (PMID 30524737, 2018). "In this study there was no such comparison, since all were obese, butwhen separated by degree of obesity, the most obese had no higher CRP value." (PMID 30539977, 2018). "The present study therefore supports an inverse relationship between CK and CRP by its presence in the general population, but an influence of obesity is not confirmed from these data." (PMID 29813131, 2018). "The association between obesity and physical HRQOL was rendered non-significant in models including CRP." (PMID 30123515, 2018). "Decreased levels of CRP in women with PCOS after metformin treatment may be related to PCOS’ biochemical characteristics, such as obesity and IR." (PMID 28404960, 2017). "In a pooled analysis of surveys that measured malaria, stunting was associated with elevated AGP but not CRP in PSC, and obesity was associated with both elevated CRP and AGP in WRA." (PMID 28615263, 2017).
Obesity (continued). "Some of these molecules antagonise effects of insulin such as leptin or TNF-α, while others have beneficial effects such as adiponectin, with evidence that plasma CRP relates to insulin resistance independent of obesity." (PMID 28193219, 2017). "Similarly to PS, subclinical inflammation induced by obesity is characterized by increased production of inflammatory cytokines IL-6 and TNF-α and higher C-reactive protein (CRP) levels." (PMID 28947858, 2017). "CRP is an important nonspecific biochemical marker of inflammation which is synthesized in both liver as well in adipose tissue in the presence of obesity." (PMID 29049355, 2017). "In this prospective, nested, case–control study, we examined the role of CRP in predicting the development of incident T2D independent of obesity, lifestyle and blood lipid profiles in Chinese adults." (PMID 28178951, 2017). "Similarly, inflammatory markers such as C-reactive protein (CRP) and erythrocyte sedimentation rate (ESR) can be affected by a large number of variables, including age and obesity, and as such offer limited specificity in patient identification." (PMID 28091549, 2017). "Furthermore, we demonstrate that long-term T therapy in men with various classes of obesity reduced blood glucose, HbA1c, SBP and DBP, CRP and improved lipid profiles." (PMID 26219417, 2016). "Yet, no increase in CRP concentration was observed for the HF pigs, eventually due to the limited length of the experiment, not allowing the development of a real obesity in HF pigs." (PMID 27223303, 2016). "An inverse correlation between CRP and CML in blood has also been found in obesity, and it has been hypothesized that inflammation may result in trapping of CML in tissue." (PMID 27529340, 2016). "Metabolic inflammation and excessive adipose mass (obesity) increase the level of nonspecific inflammatory biomarkers, such as CRP." (PMID 28097156, 2016). "The predictive value of hs-CRP did not seem to be fully independent of obesity in several but not all studies." (PMID 26824043, 2016). "For instance, one study found that consumption of n-3 PUFAs did not affect the plasma levels of CRP among individuals who suffer from dyslipidaemia and obesity." (PMID 27544079, 2016). "The evidence of a linear relation between obesity and hs-CRP found in healthy people does not seem to occur in HF patients." (PMID 27759823, 2016). "We further adjusted this model for obesity indicators, BMI and waist circumference, and no changes were seen with CRP." (PMID 26632325, 2016). "Obesity promotes a state of chronic low-grade inflammation in WAT mediated by increased plasma concentrations of several adipokines, including TNF-α, IL-6, and C-reactive protein (CRP)." (PMID 26580647, 2015). "Lep values had relationship with obesity, MetS, and CRP, but not with gout-related variables and course during 6 and 12 months follow-up." (PMID 26131838, 2015). "Multiple regression analysis demonstrated an association of hs-CRP levels with AHI (F = 3.293, P = 0.033), which was independent of obesity." (PMID 25538852, 2014). "In keeping with these observations, a recent study in adults with obesity and OSAS has shown that the combined use of CPAP and weight-loss did not reduce serum CRP levels more than either intervention alone." (PMID 25238542, 2014). "On the other hand, there is increased prevalence of obesity among patients with OSAS, and previous evidence suggests that adipose tissue can produce proinflammatory factors, such as C-reactive protein (CRP), tumor necrosis factor-α (TNF-α), interleukin-6 (IL-6), and interleukin-8." (PMID 25538852, 2014). "Yudkin’s study showed that in 107 nondiabetic subjects, increased plasma concentration of CRP was closely related to the components of insulin resistance syndrome, such as obesity, hypertriglyceridemia and low HDL-c." (PMID 24558466, 2014).
Obesity (continued). "Earlier studies have also revealed that both IL-6 and TNF increase hepatic production of C-reactive protein (CRP), a major acute phase protein, which is a nonspecific but sensitive marker of infection and tissue inflammation that is increased in obesity." (PMID 24877058, 2014). "Analysis of LPC species revealed a decrease of most species in obesity and negative correlations with C-reactive protein (CRP) and body mass index (BMI)." (PMID 25340546, 2014). "As a result, obesity is now recognized as a state of low-grade systemic inflammation characterized by high circulating levels of inflammatory molecules, such as TNF-α, IL-6, and C-reactive protein (CRP)." (PMID 24324381, 2013). "The obese women had significantly higher CRP-values than the overweight women, which is not surprising given that obesity is considered a pro-inflammatory state." (PMID 23667649, 2013). "Previous studies on sex differences in the relationship of leptin to CRP showed that either the relationship was similar in men and women independent of obesity or that the independent relationship was seen only in women." (PMID 24371525, 2013). "This inflammation is characterized by increased serum concentrations of C-reactive protein (CRP), interleukin 6 (IL-6), IL-8, monocyte chemotactic protein-1 (MCP-1), and tumor necrosis factor alpha (TNFα) in patients and different animal models of obesity." (PMID 23819063, 2013). "We also showed that the time spent in sedentary behaviours positively correlated with the quantitative CRP levels, independent of physical activity and obesity." (PMID 22524121, 2012). "Our findings also, for the first time, point to a significant association between the time spent on sedentary behaviour and the quantitative CRP levels, independent of physical activity and obesity." (PMID 22524121, 2012). "Factors believed to be resulting from obesity were not included in the model (blood pressure, cholesterol, glucose CRP, adiponectin)." (PMID 22693553, 2012). "There is an upregulation of inflammatory markers such as interleukin-6, interleukin-6 receptor and acute phase protein CRP in Acute Myocardial Infarction (AMI) patients but the exact mechanism linking obesity and inflammation is not known." (PMID 22891684, 2012). "Some authors have documented the relationship between hs-CRP and diabetes type 2, with or without obesity." (PMID 22309488, 2012). "WHR was the only obesity indicator that did not perform well in men in identifying individuals with a high hs-CRP level after adjusting for age, smoking, alcohol drinking, and betel nut chewing." (PMID 20875142, 2010). "In these studies, the relationship of CRP and insulin resistance was no longer evident after adjusting for various parameters related to obesity." (PMID 21167068, 2010). "The reduced aortic compliance and distensibility seen in individuals with uncomplicated obesity was unrelated to the inflammatory status, as CRP was not correlated to aortic function." (PMID 18275595, 2008). "Plasma C-reactive protein (CRP), tumor necrosis factor-α (TNF-α), and interleukin-6 (IL-6), markers of inflammation, levels are elevated in subjects with obesity, insulin resistance, essential hypertension, type 2 diabetes, and CHD, suggesting that low-grade systemic inflammation occurs in them." (PMID 18348729, 2008). "Plasma levels of inflammatory markers such as CRP, TNF-α, and IL-6 are elevated in obesity, insulin resistance, essential hypertension, type 2 diabetes, CHD, and metabolic syndrome X, suggesting that all these disorders are associated with low-grade systemic inflammation." (PMID 18078524, 2007). "Plasma levels of C-reactive protein (CRP), tumor necrosis factor-α (TNF-α), and interleukin-6 (IL-6), markers of inflammation are elevated in subjects with obesity, insulin resistance, essential hypertension, type 2 diabetes, and CHD both before and after the onset of these diseases." (PMID 18078524, 2007).
Obesity (continued). "Additionally, CRP levels are influenced by factors independent of oxidative stress, including obesity-related adipokine secretion, subclinical infections, and genetic variants (CRP gene polymorphisms)." (PMID 41607455, 2026). "In patients with inflammation (elevated CRP) or obesity, cystatin C levels may rise independent of filtration changes." (PMID 41516239, 2025). "Firstly, obesity is characterized by chronic inflammation, and while inflammatory biomarkers may increase in obese patients, PJI represents a more acute and severe form of inflammation that can have a greater impact on markers like CRP and ESR." (PMID 40041151, 2025). "For instance, some research shows that in cases of simple obesity, C-reactive protein (CRP) levels may not significantly increase, indicating individual differences in inflammation's role in obesity-related metabolic disorders." (PMID 40487757, 2025). "FIB-4, CRP/Alb, and TG/HDL may serve as complementary indicators of metabolic and fibrotic burden, reflecting the inflammatory–metabolic profile of individuals with obesity." (PMID 41302334, 2025). "Lean diabetics demonstrated relatively higher adiponectin but elevated inflammatory markers, particularly CRP and IL-6, suggesting that chronic low-grade inflammation and β-cell dysfunction, rather than obesity-related insulin resistance, are central to disease pathogenesis in this subgroup." (PMID 41523554, 2025). "However, it has also been shown that high-intensity interval exercise does not affect insulin, lipid profile, C-reactive protein, and interleukin-6 in people with overweight or obesity." (PMID 40003575, 2025). "Comorbidities did not affect CRP levels among patients with obesity (p > 0.999)." (PMID 40005412, 2025). "The strong negative correlation between CRP, an indicator of increased inflammation in obesity, and HDL suggests that elevated inflammation levels may reduce HDL levels, which in turn may diminish the cardiovascular protective effects of HDL." (PMID 40900465, 2025). "An alternative explanation, alongside the 'ceiling effect,' is that these non-specific, systemic markers (NLR, CRP) are simply not sensitive enough to detect the specific, low-grade inflammation associated with T2DM pathogenesis once high-grade obesity-driven inflammation is already present." (PMID 41426805, 2025). "However, at baseline, serum levels of CRP/hs-CRP were notably higher in patients with obesity compared to those without obesity, indicating a high pro-inflammatory status." (PMID 40422620, 2025). "Notably, CRP exhibited a significant mediating effect in the obesity and depressive symptoms link, whereas NLR did not." (PMID 40926826, 2025). "Ginger also significantly lowered fasting plasma glucose, glycated hemoglobin (HbA1c), insulin, CRP, and the homeostatic model assessment of insulin resistance (HOMA-IR) index compared to the placebo group in patients with DM2, a common comorbidity in individuals with obesity." (PMID 40733199, 2025). "The serum levels of CRP and IL-6 were higher in the sarcopenic obesity group, while the serum glucose was significantly higher in patients with obesity without sarcopenia than in the sarcopenic obesity group." (PMID 38921440, 2024). "Additionally, the study revealed that children with SDB exhibited severity-dependent increases in plasma C-reactive protein (CRP) and IL-6 levels, regardless of their obesity status." (PMID 38672697, 2024). "Children with obesity, regardless of family history determinants, had higher blood levels of CRP." (PMID 38238301, 2024). "When stratified by sex, obesity, hs-CRP category, a statistically significant correlation was only observed in female (OR = 1.83; 95% CI, 1.20–2.79), those without obesity (OR = 2.07; 95% CI, 1.29–3.31), and those without hyper hs-CRP (OR = 2.11; 95% CI, 1.33–3.35)." (PMID 38297351, 2024).